KLF2 (KLF transcription factor 2)
Diseases named in the same sentence as KLF2 in open-access papers (continued):
Sharing a sentence is not in itself a finding about the gene and the disease.
Obesity (8 papers, 2006 to 2025). Accumulation of substantial excess body fat. "Taken together, these data suggest that loss of myeloid KLF2 promotes a leptin-resistant phenotype, likely contributing to obesity in the basal and diet-induced states." (PMID 33208733, 2020). "Although pair-feeding underscores the importance of processes downstream of microglial activation on metabolic disease, we wanted to determine if activation of microglia by loss of KLF2 was a major driver of food intake, obesity, and diabetes." (PMID 33208733, 2020). "Together, these data indicate that conditions known to contribute to obesity are associated with loss of KLF2 expression in macrophages, likely contributing to metaflammatory disease." (PMID 33208733, 2020). "Because anthropometric variables and obesity status differ significantly according to gender, we assessed the impact of the KLF2 polymorphisms in men and women separately in the analyses." (PMID 16542423, 2006). "While loss of myeloid KLF2 contributes to a significant obesity phenotype at baseline, we sought to explore whether adding a metaflammatory stimulus such as HFD would exacerbate genotype-dependent differences in metabolic disease." (PMID 33208733, 2020). "In our model, obesity was associated with diminished KLF2 transcription in humans and mice and, therefore, may reveal a mechanism by which metaflammation arises." (PMID 33208733, 2020). "From these results, it seems unlikely that the genetic variability of the KLF2 gene plays a mayor role in susceptibility to T2D or obesity." (PMID 17688680, 2007). "The major limitation of the study may be that only two SNPs in KLF2 were studied and therefore we can not totally exclude that other SNPs in or nearby (especially in regulatory regions) the KLF2 gene might be associated with obesity traits." (PMID 16542423, 2006). "Obesity upregulated the expression of Klf2, Klf4, Klf6 and Klf9 at all timepoints in heart art, cap and ven ECs." (PMID 36400935, 2022). "Here, we identify myeloid Krüppel-like factor 2 (KLF2) as an essential regulator of obesity and its sequelae." (PMID 33208733, 2020). "KLF2 is reduced in response to inflammatory stimuli encountered in obesity, which subsequently permits unrestrained central and peripheral metaflammation, ultimately contributing to obesity and metabolic disease." (PMID 33208733, 2020). "Given the widespread transcriptional impact of KLF2 in networks related to obesity and metabolic disease, we sought to determine if diet-induced obesity affects myeloid KLF2 expression in in mammals." (PMID 33208733, 2020). "Prohibiting the initial diet-induced reduction in KLF2 expression appears to protect against obesity and insulin resistance as demonstrated by the K2Tg mouse model." (PMID 33208733, 2020). "We found captured, MVAs expressed significantly higher levels of TNFA, CEBPA, and KLF2 transcripts than MSA, all of which favor reduced levels of adipogenesis in VAT and higher levels of RETN and SERPINs, which are linked to obesity-related disease risk." (PMID 27462403, 2016). "In other contexts, statins may affect macrophages in a favorable manner due to their ability to induce KLF2: a recent study revealed that myeloid KLF2 reduces metabolic inflammation in peripheral and central tissues in a mouse model of obesity." (PMID 34830364, 2021). "Finally, overexpression of myeloid KLF2 protects mice from HFD-induced obesity and insulin resistance." (PMID 33208733, 2020). "Given this, we hypothesized that if myeloid KLF2 expression were maintained despite HFD stimulus, mice would be protected against obesity and metabolic disease." (PMID 33208733, 2020). "Similarly, genes encoding circadian clock regulators (Dbp, Nr1d1 and Nr1d2), KLF transcription factors (Klf2 and Klf6) and cell signaling molecules (Rhob and Shank3) were also upregulated in sustained obesity (cohort 2) but not in the reversion group (cohort 3)." (PMID 36400935, 2022).
prostate carcinoma (8 papers, 2020 to 2025). A carcinoma that arises from epithelial cells of the prostate gland. "Prostate cancer-derived TDEVs contain circFMN2, which, upon binding to HuR, reduces the HuR-KLF2 interaction, inhibits KLF2 expression, and subsequently decreases RNF128 transcription, collectively promoting tumor cell proliferation, invasion, and migration." (PMID 41459253, 2025). "LncRNA GHET1 reduces KLF2 expression to trigger HIF-1α/Notch1 signaling in increasing prostate cancer progression." (PMID 35773731, 2022). "Additionally, despite a previous study in prostate cancer describing an inhibitory effect of KLF2 on migration, we found decreased nuclear KLF2 following rapamycin incubation." (PMID 36214828, 2023). "In addition, induction of KLF2 along with autophagy in prostate cancer cells was also documented." (PMID 35552354, 2022). "Upregulated GHET1 increases prostate cancer proliferation through inducing HIF-1α and Notch 1 signal via negative regulation of Kruppel-like factor 2 (KLF2)." (PMID 36229883, 2022). "Notably, silencing GHET1 promotes KLF2 expression, leading to HIF-1α/Notch1 inhibition and subsequent decrease in prostate cancer progression." (PMID 35773731, 2022).
diabetes (7 papers, 2020 to 2025). "However, in diabetes, the underlying epigenetic mechanism of KLF2 and KLF4 regulation in EC still remains elusive." (PMID 34685528, 2021). "While miR-92a alone cannot dysregulate KLF2 in healthy cardiac microvasculature, inhibition of micro-RNA in diabetes can bring about benefits." (PMID 36768805, 2023). "We show that KLF2 dysregulation in diabetes correlates with greater monocyte adhesion as well as migratory defects in cardiac microvascular endothelial cells." (PMID 36768805, 2023). "Restoring KLF2 function in vascular disease conditions, such as diabetes, is therefore expected to be of therapeutic value." (PMID 36768805, 2023). "Others found that miR-92a with diabetes could inhibit apoptosis induced by a high-glucose environment and could increase insulin secretion by targeting Kruppel Like Factor 2 (KLF2)." (PMID 36874371, 2022). "Metformin, an insulin‐sensitizing drug used in the management of type 2 diabetes mellitus (T2DM), increases the expression of Nrf2 and KLF2." (PMID 39092773, 2024). "To determine whether this applies to our CMECs and whether the observed dysregulation of KLF expression in diabetes is linked to the observed MEF2D dysregulation in our diabetic models, we knocked down MEF2A or MEF2D in nondiabetic HCMECs and analyzed KLF2 and KLF4 gene expression." (PMID 36768805, 2023). "Notably, metformin, an insulin‐sensitizing drug used as first‐line treatment for type 2 diabetes mellitus (T2DM), improves Nrf2 and KLF2 expression." (PMID 39092773, 2024).
lymphoma (7 papers, 2014 to 2023). A malignant (clonal) proliferation of B- lymphocytes or T- lymphocytes which involves the lymph nodes, bone marrow and/or extranodal sites. "Accordingly, KLF2 loss-of-function mutations as found in human lymphoma cells impaired KLF2-mediated NF-κB suppression in a B lymphoma cell line, a topic that will be discussed later in the review article." (PMID 37251374, 2023). "The loss of function of KLF2 is associated with diseases, such as arteriosclerosis, adipogenesis, thrombosis, and lymphoma." (PMID 37251374, 2023). "We conclude that a possibility of lymphoma should be considered in patients with KLF2 genetic variant." (PMID 36466816, 2022). "Davide Rossi from Gaidano’s group in Turin identified the transcription factor KLF2 as frequently mutated in splenic marginal zone lymphoma, adding to the genetic subdivision of lymphomas." (PMID 25183998, 2014). "In lymphoma cells, mutated KLF2 delocalizes from the nucleus into the cytoplasm and is not able to inhibit the NF-κB signaling activated by upstream pathways, including the BCR and TLR pathways." (PMID 29657712, 2018). "KLF2 knock-out led to the deregulation of B-cell differentiation and trafficking, but was not sufficient to induce lymphoma in a murine model." (PMID 35454811, 2022). "In a murine model, KLF2 gene knock-out is not sufficient to induce lymphoma but results in deregulation of B-cell differentiation and trafficking." (PMID 29989027, 2018).
multiple myeloma (7 papers, 2016 to 2025). "We were particularly interested in the e2QTL for KLF2 that represent a GWAS risk variant for multiple myeloma (MM) and are present among all stimuli associated to BER and NER (r2 = 0.833 – 0.983)." (PMID 39623312, 2024). "Thus, on the one hand, there are some studies associating KLF2 with an oncogenic role, as in the case of multiple myeloma or pancreatic tumors, whereas in other models, it seems to have a character closer to tumor suppression, as in hepatocarcinoma or, more recently, in renal cancer." (PMID 35884568, 2022). "To identify mechanisms responsible for the plasma cell increase, we investigated KLF2, a transcription factor previously shown to modulate multiple myeloma cell adhesion and homing of plasma cells." (PMID 34642171, 2022). "We aimed to investigate the relationship among epidermal growth factor–like protein-7 (EGFL7), integrin subunit beta 3 (ITGB3), and Kruppel-like factor 2 (KLF2) expressions and their clinical implication in multiple myeloma (MM)." (PMID 34635968, 2022). "KLF2 is a gene previously shown to regulate homing of plasma cells in multiple myeloma." (PMID 34642171, 2022). "Here, the authors reveal a role for the histone demethylase KDM3A in the survival of this haematologic cancer, and show that mechanistically KDM3A removes H3K9 methylation from the promoters of KLF2 and IRF4, genes essential for myeloma cell survival." (PMID 26728187, 2016).
osteosarcoma (7 papers, 2020 to 2023). A usually aggressive malignant bone-forming mesenchymal neoplasm, predominantly affecting adolescents and young adults. "A previous study suggested that highly expressed circLRP6 was related to the worse overall survival in osteosarcoma, and circLRP6 promoted osteosarcoma tumorigenesis by downregulating KLF2 and APC expression level." (PMID 34158077, 2021). "CircRNA LRP6 accelerates the development of osteosarcoma through regulating KLF2 and APC expressions." (PMID 33958507, 2021). "p21 and KLF2 play vital roles in osteosarcoma progression, such as miR-95-3p/p21 axis, and involvement of KLF2 in drug resistance to doxorubicin." (PMID 32518528, 2020). "For example, CircRNA LRP6 promotes osteosarcoma development by targeting KLF2 and APC." (PMID 34224315, 2021). "The result indicated that CCL28, KLF2 and TNFSF18 did not significantly affect cell apoptosis, while the knockdown of HMGB1 and TLR4 significantly increased the proportion of apoptotic of osteosarcoma cells." (PMID 36204682, 2022).
ovarian carcinoma (7 papers, 2014 to 2022). A malignant neoplasm originating from the surface ovarian epithelium. "Then, LINC00702 was reported to accelerate the progression of ovarian cancer by acting with EZH2 to repress KLF2 transcription." (PMID 36566321, 2022). "Consistent with this notion, KLF2 expression is diminished in a variety of human malignancies including prostate, breast, and ovarian cancers, suggesting that KLF2 may be a tumor suppressor gene." (PMID 24899581, 2014). "Moreover, EZH2 in interaction with LINC00702, could suppress the transcription of KLF2 in ovarian cancer." (PMID 34462420, 2021). "Findings come mostly from experimental studies suggesting that KLF2, KLF4, KLF6 and KLF11 act as tumour suppressors in ovarian cancer while KLF5, KLF8 and KLF9 might have a potential role in disease development and progression." (PMID 33250051, 2020). "Results of bioinformatic analysis on KLF2 and KLF5 were actually not in line with previous literature data indicating that KLF2 may act as tumor suppressor in ovarian cancer, while KLF5 may behave as an oncogene." (PMID 33250051, 2020).
rheumatoid arthritis (7 papers, 2017 to 2024). A chronic, systemic autoimmune disorder characterized by inflammation in the synovial membranes and articular surfaces. "The emerging role of KLF2 in regulation of osteoclastic differentiation is examined, specifically in the context of rheumatoid arthritis in which it has been most extensively studied among the musculoskeletal diseases." (PMID 32477372, 2020). "Recent reports detail work done in a K/BxN serum-induced model of rheumatoid arthritis which further illumines the role of KLF2 in regulating disease progression." (PMID 32477372, 2020). "Krüppel‐like factor 2 (KLF2) critically regulates activation and function of monocyte, which plays important pathogenic role in progressive joint destruction in rheumatoid arthritis (RA)." (PMID 30506878, 2019). "Rheumatoid arthritis (RA) is an immune-mediated inflammatory disease, and Krüppel-like factor 2 (KLF2) regulates immune cell activation and function." (PMID 31426355, 2019). "For example, KLF2 plays important role in regulating adipogenesis and inflammatory disease conditions, such as, rheumatoid arthritis, vascular diseases, chronic infections and various malignancies." (PMID 29125549, 2017). "Further, due to chronic inflammatory condition found in rheumatoid arthritis, we explored the involvement of KLF2 in pathogenesis and possible regulation of rheumatoid arthritis." (PMID 29125549, 2017). "KLF2 is a transcription factor that orchestrates the expression of a battery of genes involved in a wide variety of inflammatory disease conditions, such as rheumatoid arthritis, atherosclerosis, and chronic kidney disease." (PMID 31827706, 2019). "Due to the role of KLF2 as a negative regulator of monocyte activation and function, we focused on the role of KLF2 in rheumatoid arthritis, which is a chronic inflammatory disease, with severe inflammation and destruction of synovial joints in bones and ligaments." (PMID 29125549, 2017). "To date, two studies have reported the pathological and biological role of KLF2 in rheumatoid arthritis (RA)." (PMID 31827706, 2019). "KLF2 decreases the enrichment of active histone marks H3K9Ac and H4K8Ac and HAT (P300, PCAF) on the MMP‐9 promoter region along with lower migration of activated monocytes to the rheumatoid arthritis sites." (PMID 39263604, 2024).
cerebral cavernous malformation (6 papers, 2016 to 2025). A disorder characterized by malformations in the structure of the capillaries in the brain. "Because both KLF2 and KLF4 were shown to be downstream of increased MEKK3-MEK5-ERK5 signaling in cerebral cavernous malformations, we next examined the expression of KLF2 and KLF4 in shear stress-exposed HUVECs." (PMID 37583551, 2023). "The endothelial CCM (Cerebral Cavernous Malformation) complex, comprising KRIT1 (Krev1 interaction trapped gene 1), CCM2 (Malcavernin), and CCM3 (Programmed cell death protein 10), suppresses the expression of KLF2 and KLF4." (PMID 40362576, 2025).
colon cancer (6 papers, 2021 to 2024). "Through the upregulation of the tumor suppressor gene KLF2, EOs from four different regions reduced the development and proliferation of colon cancer cells and the production of MMP9." (PMID 38365676, 2024). "Colon cancer exosome miR-25-3p targets KLF2 and KLF4 of vascular endothelial cell, affecting their function." (PMID 34179017, 2021).
Hepatic steatosis (6 papers, 2018 to 2024). Steatosis is a term used to denote lipid accumulation within hepatocytes. "The introduction of KLF2 through adenovirus-mediated overexpression in healthy mice amplifies hepatic steatosis by increasing the expression of the Cd36 gene." (PMID 37949368, 2024). "Adenovirus-mediated overexpression of KLF2 in healthy mice promotes hepatic steatosis through increased Cd36 gene expression, TG synthesis (Gpat1, Agpat1, Dgat1), and lipid storage (Perilipin 1, Perilipin 2, Cidea) gene expression." (PMID 36902112, 2023). "Significant anti-hepatic steatosis effects, including decreased number of lipid droplets and expression of Klf2 mRNA, were detected in the liver of the HFD + EMfC treated group." (PMID 32948162, 2020). "Klf2 is known to promote hepatic steatosis through upregulation of Cd36 expression and Klf2 mRNA expression was increased in rats fed high Cho." (PMID 31921324, 2020). "KLF2 is also involved in hepatic steatosis and is significantly elevated in the livers of obese mice." (PMID 29942807, 2018). "Adenovirus-mediated overexpression of Klf2 induces accumulation of triglycerides in lean mice, while silencing Klf2 ameliorates liver steatosis in obese ob/ob mice." (PMID 29942807, 2018). "Additionally, transgenic mice (ALB-Klf2) that overexpressed Klf2 in the liver developed liver steatosis after being fed a normal diet." (PMID 37949368, 2024). "However, our study has found that KLF2 promotes liver steatosis by increasing lipogenesis through activation of the SREBP1 pathway." (PMID 37949368, 2024). "KLF2, a transcription factor involved in regulating the expression of genes in various tissues and cells, including the liver, has been found to be increased in the liver during liver steatosis." (PMID 37949368, 2024). "Thus, we hypothesize that Klf2-induced liver steatosis may occur through an increase in lipogenesis." (PMID 37949368, 2024). "This suggests that there may be other mechanisms, other that KLF2-induced upregulation of CD36, involved in KLF2-induced liver steatosis." (PMID 37949368, 2024). "In contrast to the direct role of KLF2 in hepatocyte biology, KLF4 indirectly influences the hepatocyte genetic program through M2 polarization in Kupffer cells and release of IL-10, which prevents the development of HFD-induced hepatic steatosis and NASH pathogenesis." (PMID 36902112, 2023).